GRAMD1B (GRAM domain containing 1B)
Diseases named in the same sentence as GRAMD1B in open-access papers:
GRAMD1B is named in the same sentence as 57 diseases in open-access papers, as found by Europe PMC text mining. Sharing a sentence is not in itself a finding about the gene and the disease. The quoted sentences say what the papers report.
breast carcinoma (9 papers, 2018 to 2023). "Nonetheless, further analyses are required to determine the mechanism underlying the interaction between GRAMD1B and Rho GTPases in modulating breast cancer cell migration." (PMID 29934528, 2018). "GRAMD1B was shown to inhibit breast cancer cell proliferation and promote cell death by deactivating JAK/STAT signaling." (PMID 37237509, 2023). "Khanna’s study has proved that GRAMD1B regulates cell migration in breast cancer cells through JAK/STAT and Akt signalling." (PMID 36056349, 2022). "By contrast, GRAMD1B expression was down-regulated by the JAK2 inhibitor AG490, suggesting that the JAK/STAT cascade regulates GRAMD1B expression in breast cancer cells." (PMID 29934528, 2018). "In this study, JAK/STAT signaling was found to positively regulate GRAMD1B expression in the breast cancer MDA-MB-231 cells." (PMID 29934528, 2018). "Lastly, our epistasis analysis suggested the pivotal function of GRAMD1B in mediating the inhibitory effect of JAK/STAT signaling on Akt activity in breast cancer cells." (PMID 29934528, 2018). "Here, we showed that GRAMD1B expression is upregulated on IL-6 but downregulated upon treatment with the JAK2 inhibitor AG490 in the breast cancer MDA-MB-231 cells." (PMID 29934528, 2018). "Nonetheless, our study suggests that GRAMD1B is a key signaling molecule that functions to inhibit cell migration in breast cancer, providing the foundation for its development as a novel biomarker in breast tumors." (PMID 29934528, 2018). "While Gramd1b knockdown cells almost entirely covered the wound by 36 hours, only ~40% of the wound had been covered by control cells (b’), suggesting that GRAMD1B negatively regulates cell migration in breast cancer cells." (PMID 29934528, 2018). "By doing so, GRAMD1B, in turn, might contribute to breast cancer, as LDL-derived cholesterol has been extensively described to promote the growth, proliferation, and migration of breast cancer cells, specifically of TNBC cells." (PMID 38250802, 2023). "Taken together, our results suggest that GRAMD1B is a key signaling molecule that functions to inhibit cell migration in breast cancer by negating both JAK/STAT and Akt signaling, providing the foundation for its development as a novel biomarker in breast cancer." (PMID 29934528, 2018). "Since our findings revealed a novel central role of GRAMD1B in negatively regulating the JAK/STAT and Akt pathway, it is conceivable that GRAMD1B may function to inhibit breast cancer cell proliferation and promote cell death." (PMID 29934528, 2018). "Moreover, we provided evidence that GRAMD1B modulates breast cancer cell migration through the regulation of both JAK/STAT and Akt signaling." (PMID 29934528, 2018). "Additionally, induction of JAK/STAT3 signaling cascade activation, mesoderm-specific transcript (MEST) stimulates Twist expression, while inhibition of the JAK/STAT3 and protein kinase B (Akt) cascade, GRAM domain-containing protein 1B (GRAMD1B) prevents breast cancer cell migration." (PMID 34488773, 2021). "However, the role of GRAMD1B in breast cancer is still largely unknown." (PMID 37237509, 2023). "In summary, we believe that by targeting and downregulating GRAMD1B, miR-4646-5p exerts a tumor-suppressive effect, as it thereby might impair the transport and thus the use of exogenous cholesterol, which has been reported to constitute a vital pro-oncogenic source for breast cancer cells." (PMID 38250802, 2023). "In contrast, JAK2 inhibitor AG490 can downregulate the expression of GRAMD1B in breast cancer MDA-MB-231 cells, suggesting that JAK/STAT signaling controls the expression of GRAMD1B in breast cancer cells." (PMID 37237509, 2023). "GRAMD1B inhibits cell migration by negatively regulating JAK / STAT and AKT signal transduction in breast cancer." (PMID 38039294, 2023).
breast carcinoma (continued). "Here, we showed that JAK/STAT signaling positively regulates GRAMD1B expression, which in turn negates the signaling in breast cancer cells, signifying the existence of a negative feedback mechanism." (PMID 29934528, 2018). "Moreover, it was recently discovered that GRAMD1B is a downstream target of JAK-STAT signaling in gastric and breast cancer cell lines, and it is a key signaling molecule able to inhibit cell migration in breast cancer." (PMID 36553660, 2022).
schizophrenia (4 papers, 2021 to 2025). A major psychotic disorder characterized by abnormalities in the perception or expression of reality. "Notably, GRAMD1b dysfunction is associated with various neurological disorders, including schizophrenia, intellectual disability, and multiple sclerosis, suggesting critical roles of GRAMD1b (and potentially other GRAMD1s) in maintaining neuronal development and function." (PMID 37735529, 2023). "GRAMD1B was identified as a locus for schizophrenia in multiple studies, a condition that has been linked with anxiety." (PMID 40537477, 2025).
chronic lymphocytic leukemia (3 papers, 2013 to 2022). "In human, a polymorphism in the GRAMD1B gene has been associated with susceptibility to chronic lymphocytic leukemia." (PMID 24965341, 2014). "Interestingly, although no studies demonstrated a relationship between GRAMD1B and serum IgE levels, a GWAS has identified a SNP near GRAMD1B on chromosome 11q24.1 associated with chronic lymphocytic leukemia (CLL)." (PMID 24324648, 2013). "In esophageal carcinoma, however, ODZ4 rearranges with Exostosin Glycosyltransferase 2 (EXT2), while ODZ4 rearranges with Cell Adhesion Molecule 1 (CADM1) and Gram Domain containing 1b (GRAMD1B) in chronic lymphocytic leukemia." (PMID 35011736, 2022).
gastric cancer (3 papers, 2017 to 2023). A primary or metastatic malignant neoplasm involving the stomach. "GRAMD1B expression levels were also found to be significantly associated with clinicopathological features of the gastric cancer patients, particularly the tumor grades and lymph node status." (PMID 29383166, 2017). "To investigate if JAK/STAT-mediated transcriptional regulation of CG34394 is conserved across phyla, we examined the expression of GRAMD1B using the human gastric cancer cell lines AGS and NUGC3." (PMID 29383166, 2017). "Immunohistochemical analyses of matched normal and tumor gastric tissues revealed a decrease in GRAMD1B cytoplasmic staining but an increase in its nuclear staining as normal gastric tissue becomes aggressive diffuse-type of gastric cancer." (PMID 29383166, 2017). "Consistently, decreased cytoplasmic but increased nuclear GRAMD1B levels were detected in the more aggressive diffuse-type of gastric cancer as compared to the intestinal-type, suggesting the potential role of nuclear GRAMD1B in gastric tumor progression." (PMID 29383166, 2017). "To further investigate the role of GRAMD1B in oncogenesis, we performed immunohistochemical analyses for GRAMD1B in 63 human gastric cancer tissue with matched normal tissue samples." (PMID 29383166, 2017). "However, we noticed that there was a gradual decrease in cytoplasmic GRAMD1B but an increase in nuclear GRAMD1B as normal gastric tissue turns into aggressive diffuse-type of gastric cancer." (PMID 29383166, 2017). "Interestingly, we also detected nuclear GRAMD1B expression in our tumor samples, with the more aggressive diffuse-type of gastric cancer showing higher expression." (PMID 29383166, 2017). "Interestingly, our immunohistochemical analyses of human gastric tumor tissues uncovered a decreased cytoplasmic but an increased nuclear GRAMD1B staining in the aggressive diffuse-type of gastric cancer." (PMID 29383166, 2017). "Taken together, our study may suggest the important role of GRAMD1B in gastric cancer survival, together with JAK/STAT signaling via modulating anti-apoptotic gene expression." (PMID 29383166, 2017). "Interestingly, our immunohistochemical analysis for GRAMD1B using 63 paired gastric cancer tissue microarrays (TMAs) revealed decreased cytoplasmic but increased nuclear staining of GRAMD1B as tissue becomes malignant, implying the importance of nuclear GRAMD1B localization in gastric tumorigenesis." (PMID 29383166, 2017). "Concurrently, the diffuse-type of gastric cancer showed significantly higher amounts of nuclear staining as compared to the intestinal-type of gastric tumor (P=0.033), suggesting that nuclear localization of GRAMD1B may play an important role in the diffuse-type of gastric cancer." (PMID 29383166, 2017). "Our study also showed that GRAMD1B, together with JAK/STAT signaling, facilitates gastric cancer cell survival by modulating the expression of anti-apoptotic genes such as Bcl-xL." (PMID 29383166, 2017). "Since GRAMD1B is a novel downstream target of the JAK/STAT cascade, we first explored its role in the cell growth of gastric cancer cells." (PMID 29383166, 2017). "Consistently, GRAMD1B and JAK/STAT signaling acted synergistically to promote gastric cancer cell survival by upregulating the expression of the anti-apoptotic molecule Bcl-xL." (PMID 29383166, 2017).
glioma (2 papers, 2017 to 2022). A benign or malignant brain and spinal cord tumor that arises from glial cells (astrocytes, oligodendrocytes, ependymal cells). "There are no reports of GRAMD1B being associated with epilepsy or glioma." (PMID 35676651, 2022).
Intellectual disability (2 papers, 2021 to 2023). "We find that a mutation within the GRAM domain of GRAMD1b that is associated with intellectual disability in humans specifically impairs cholesterol sensing." (PMID 33604931, 2021). "Thus, the R189W mutation, which specifically impairs the cholesterol‐sensing property of the GRAM domain and has been associated with intellectual disability in humans, affects the ability of GRAMD1b to transfer cholesterol." (PMID 33604931, 2021). "However, the precise mechanism by which GRAM domains sense transient expansions in the accessible pool of PM cholesterol and the impact that the intellectual disability‐associated missense mutation has on GRAMD1b function both remain unknown." (PMID 33604931, 2021). "Notably, a missense mutation in the GRAM domain of GRAMD1b (R189W) was identified in a consanguineous family with moderate intellectual disability, indicating the importance of the GRAM domain in GRAMD1b function." (PMID 33604931, 2021).
Obesity (2 papers, 2021 to 2024). Accumulation of substantial excess body fat. "GRAMD1B gene expression in muscle was found associated with obesity in the mouse model, and mutations in its sequence were associated with feed efficiency in a beef cattle population with individuals from various breeds." (PMID 33401485, 2021).
ovarian carcinoma (2 papers, 2022 to 2023). A malignant neoplasm originating from the surface ovarian epithelium. "GRAMD1B was first associated with taxane resistance in ovarian cancer." (PMID 38250802, 2023). "Specifically, it was reported to play a role in chemoresistance of ovarian cancer patients, such that GRAMD1B inhibition led to an anti-tumor effect." (PMID 36056349, 2022).
triple-negative breast carcinoma (2 papers, 2023 to 2025). An invasive breast carcinoma which is negative for expression of estrogen receptor (ER), progesterone receptor (PR), and human epidermal growth factor receptor 2 (HER2). "GRAM domain-containing protein 1B (GRAMD1B)—a cholesterol transport regulator—emerges as a direct target of miR-4646-5p in triple-negative breast cancer (TNBC)." (PMID 40722703, 2025).
autoimmune disease (1 paper, 2022). A disorder resulting from loss of function or tissue destruction of an organ or multiple organs, arising from humoral or cellular immune responses of the individual to their own tissue constituents. "Filtering criteria narrowed down the list of more than 17,000 putative functional variants to one rare variant, leading to an amino acid change from serine to proline (p.S601P) in the GRAMD1B gene, for which no roles in autoimmune diseases have been reported so far." (PMID 36553660, 2022).
gastric tumor (1 paper, 2017). "Our study also showed potential oncogenic role of GRAMD1B in gastric tumor, together with JAK/STAT signaling by enhancing anti-apoptotic gene expression." (PMID 29383166, 2017).
leukemia (1 paper, 2015). A malignant (clonal) hematologic disorder, involving hematopoietic stem cells and characterized by the presence of primitive or atypical myeloid or lymphoid cells in the bone marrow and the blood. "Little is known about the human proteins, except that variation at the GramD1b locus is linked to lymphoma/leukemia, and we suggest renaming GramD1a-c as hLAMa-c." (PMID 26001273, 2015).
liver cancer (1 paper, 2023). An epithelial or non-epithelial malignant neoplasm that arises from the liver. "WD-reduced hepatic Cyp39a1 (cytochrome P450 family 39 subfamily a member 1) and increased Gramd1b (GRAM domain containing 1B) were also changed in human liver cancer and metabolic liver disease, respectively." (PMID 37571345, 2023).
melanoma (1 paper, 2023). A malignant, usually aggressive tumor composed of atypical, neoplastic melanocytes. "In addition, cholesterol overload related to GRAMD1B in melanoma would activate AP-1 program to promote tumor invasion." (PMID 37801479, 2023).
osteoporosis (1 paper, 2021). A condition of reduced bone mass, with decreased cortical thickness and a decrease in the number and size of the trabeculae of cancellous bone (but normal chemical composition), resulting in increased fracture incidence. "XPR1, SLC4A2, and GNPTAB were previously reported to be related to osteoporosis, but GRAMD1B, ITGA6, and DUSP6 have never been studied with respect to any musculoskeletal-related diseases." (PMID 34475393, 2021).
osteosarcoma (1 paper, 2023). A usually aggressive malignant bone-forming mesenchymal neoplasm, predominantly affecting adolescents and young adults. "A risk model composing of ZYX, GJA5, GAL, GRAMD1B, and CKMT2 was established for assessing osteosarcoma prognosis." (PMID 38039294, 2023). "Considering the heterogeneity between molecular subtypes defined by specific oxidative stress genes, we identified the DEGs between the two molecular subtypes and deduced a risk assessment system composing of ZYX, GJA5, GAL, GRAMD1B, and CKMT2 for the prognosis of osteosarcoma." (PMID 38039294, 2023).
tumor (8 papers, 2014 to 2023). "In brief, lower cytoplasmic GRAMD1B staining was associated with higher tumor grades (P=0.026) and lymph node involvement (P=0.005)." (PMID 29383166, 2017). "Specifically, decreased cytoplasmic expression of GRAMD1B was associated with higher tumor grades and lymph node involvement." (PMID 29383166, 2017). "GRAMD1B expression levels were also found to be reflective of several clinicopathological parameters, including tumor grade and lymph node status." (PMID 29383166, 2017). "Specifically, GRAMD1B was reported to be involved in chemoresistance of ovarian cancer patients, and silencing of this gene led to a synergistic anti-tumor effect in combination with paclitaxel." (PMID 29383166, 2017). "Consistent with the view that acquired chemoresistance is a major contributor to patient mortality from OvCa, reducing GRAMD1B expression increased overall survival in OvCa patients and decreased tumour burden in mouse models." (PMID 24965341, 2014). "We thus conclude that GRAMD1B may partly contribute to the diverse tumor-suppressive effects of miR-4646-5p in TNBC." (PMID 38250802, 2023). "By whole transcriptome analysis, we not only observed that miR-4646-5p downregulates many oncogenic factors, like tumor-promoting cytokines and migration- and invasion-related genes, but were also able to identify a direct target, the GRAM domain-containing protein 1B (GRAMD1B)." (PMID 38250802, 2023). "Furthermore, while GRAMD1C expression was decreased in advanced-stage tumors, the expression of GRAMD1A and GRAMD1B showed an opposite pattern, with increased expression in late-stage tumor samples compared to early-stage tumor samples." (PMID 36270994, 2022). "GRAMD1B was found to be localized in both cytoplasm and nucleus of normal and tumor tissues." (PMID 29383166, 2017). "A case-wise comparison of cytoplasmic and nuclear staining of tumor tissues versus matched normal tissues confirmed the decrease in cytoplasmic staining (P=0.02) and the increase in nuclear staining (P=0.176) of GRAMD1B." (PMID 29383166, 2017). "Similarly, a positive correlation for GRAMD1B and pSTAT3 staining was observed in tumor gastric tissues with a Spearman’s correlation coefficient of 0.23 (P=0.08)." (PMID 29383166, 2017). "Moreover, we discovered that downregulation of GRAMD1B phenocopies the growth-reducing effect of miR-4646-5p, suggesting that the downregulation of GRAMD1B might contribute to the tumor-suppressive properties of miR-4646-5p." (PMID 38250802, 2023). "As overall survival is also affected by invasive and migration capabilities of the tumor, we analyzed migration of 786-O cells depleted of GRAMD1A, GRAMD1B and GRAMD1C using a wound-healing assay." (PMID 36270994, 2022). "In summary, these results indicate that GRAMD1B itself may act as an oncogenic factor in TNBC and can thus partly explain the tumor-suppressive effects of miR-4646-5p, which we discovered to directly bind to and downregulate GRAMD1B mRNA." (PMID 38250802, 2023).
cancer (2 papers, 2018 to 2023). A tumor composed of atypical neoplastic, often pleomorphic cells that invade other tissues. "Further analyses exploring the role of GRAMD1B in these cancer hallmarks is necessary to provide a deeper understanding into its exact function in regulating breast tumorigenesis." (PMID 29934528, 2018). "Regarding the role of GRAMD1B in cancer, there are contradicting reports." (PMID 38250802, 2023). "Therefore, we speculate that upregulation of GRAMD1B, despite causing decreased SREBP-2 activation and cholesterol biosynthesis, would be beneficial for cancer cells, as it could support their increased uptake, storage, and use of exogenous cholesterol." (PMID 38250802, 2023).
GRAMD1B also shares sentences with these, for which no sentence is quoted: infection (22 papers); mucormycosis (7); mycoses (5); aspergillosis (3); acute kidney injury (2); Hypercholesterolemia (2); hypokalaemia (2); anemia (1); Anxiety (1); Arthritis (1); atherosclerosis (1); autosomal recessive intellectual disability (1); bipolar disorder (1); breast tumors (1); clear cell renal carcinoma (1); cryptococcosis (1); diffuse cutaneous Leishmaniasis (1); epilepsy (1); esophageal carcinoma (1); hematological malignancies (1); hypogonadism (1); inflammatory skin disease (1); invasive candidiasis (1); Legionnaires' disease (1); leishmaniasis (1); leprosy (1); lung carcinoma (1); Lymphadenopathy (1); lymphoma (1); metabolic disease (1).
A further 9 diseases each share a sentence with GRAMD1B in 1 paper.